TTN (titin)
Diseases named in the same sentence as TTN in open-access papers (continued):
Sharing a sentence is not in itself a finding about the gene and the disease.
Arrhythmia (23 papers, 2015 to 2026). Any cardiac rhythm other than the normal sinus rhythm. "We have identified a large number of VUS in the TTN gene from a cohort of samples from patients suffering cardiac diseases associated with SCD or suddenly dead with suspicions of cardiac arrhythmia." (PMID 26516846, 2015). "While TTN truncating variants (TTNtvs) have been causally linked to arrhythmia and cardiomyopathy syndromes, the role of missense variants (mvs) remains unclear." (PMID 39677424, 2025). "Future investigations in arrhythmia susceptibility under stress conditions could further strengthen mechanistic insights of the TTN variant in arrhythmogenesis." (PMID 41552678, 2025). "Titin is a giant sarcomere protein encoded by TTN, which may be associated with impaired sarcomere function caused by loss-of function variants of TTN, leading to an increased susceptibility to arrhythmia, such as early-onset AF." (PMID 37139132, 2023). "For example a loss of function in the MYL4 gene, which encodes an atria-specific myosin light chain, and a TTN gene mutation which codes a truncated variant of the giant sarcomeric protein titin predispose to early atrial fibrosis leading to cardiac arrhythmia." (PMID 36386377, 2022). "Together, these findings establish a mechanistic role for TTNmvs in AF pathogenesis and highlight IKs and FHL2 as potential therapeutic targets for TTN-related arrhythmias." (PMID 39677424, 2025). "Eight of these associations were novel (LMNA, SMAD6, HSPB9, TMEM95, KLF1, TET2, NME3, KDM5B) and 5 genes have previously been linked to arrhythmias (SCN5A, TTN, RPL3L, PKP2, PMVK)." (PMID 38390584, 2024). "One gene (TTN) was associated with both paroxysmal tachycardia (ICD10 code I47) and other cardiac arrhythmias (ICD10 code I49)." (PMID 38390584, 2024). "Most of these variants were located in genes associated with inherited arrhythmias and arrhythmic cardiomyopathies, such as MYBPC3, KCNQ1, TTN, CASQ2, GPD1L, DPP6, HCN4 and NEXN." (PMID 36008935, 2022). "In conclusion, the findings indicate the pathogenic role of the TTN variants in late-onset familial DCM associated with cardiac conduction defects and arrhythmias." (PMID 34790974, 2021). "Titin-truncating variants (TTNtvs) in the TTN gene are the most common genetic cause of DCM and may be associated with higher risk of arrhythmias in patients with DCM." (PMID 31251381, 2019). "Further characterization of endogenous signals that activate this enhancer and small molecules or genetic activation of E1 may provide new opportunities to increase TTN expression levels and overcome the deleterious effects of TTNtv that cause DCM and cardiac arrhythmias." (PMID 39688912, 2024). "DCM patients harboring TTN truncating variants likely exhibit LVRR and have better prognosis, whereas those with LMNA variants show poor response to medical therapy and are more likely to suffer from life-threatening arrhythmia and require heart transplantation." (PMID 29386531, 2018). "This Rbm20 KO mouse model exactly phenocopies our KO rat model by which the Rbm20 KO mice increase the expression of larger titin isoform, develop DCM and exhibit arrhythmias." (PMID 34523260, 2021). "One member (IV2) presenting with cardiac arrhythmias, namely paroxysmal atrial tachycardia and NSVT carried the PVs in the TTN gene." (PMID 34790974, 2021).
tibial muscular dystrophy (21 papers, 2013 to 2025). "Tibial muscular dystrophy (TMD) is caused by mutations in the TTN and manifests itself in the adult patient as weakening of the tibialis anterior muscle." (PMID 35951140, 2022). "Finnish patients that carry a mutation in another exon (Mex6) in the C-terminus of titin, which leads to a loss of C-terminal titin epitopes in histology, show late onset tibial muscular dystrophy, potentially due to a loss of binding of titin to obscurin." (PMID 30738787, 2020). "In addition, TTN is a gene encoding the giant skeletal muscle protein Titin, which is of great value in the study of tibial muscular dystrophy (TMD); while SMYD1 (the protein 1 gene of the SET and MYND domains) has an important role in sarcomere tissue." (PMID 39096856, 2024). "In humans, heterozygous variants in TTN are associated, within others, with tardive tibial muscular dystrophy (OMIM600334), a late-onset disease characterized by weakness and atrophy of the anterior compartment of the lower leg, specifically the tibialis anterior muscle." (PMID 39732776, 2024). "Finally, activation of UPR has also been observed in Tibial muscular dystrophy, a late-onset distal muscular dystrophy related to mutations in the TTN gene encoding for the titin protein." (PMID 32823799, 2020). "Some TTN mutations are associated with skeletal-muscle diseases such as tibial muscular dystrophy." (PMID 32000679, 2020). "For example, Duchenne muscular dystrophy (DMD), Becker muscular dystrophy (BMD), exhibiting absence or mutations in dystrophin, and tibial muscular dystrophy (TMD), exhibiting mutations in titin." (PMID 32937737, 2020). "In humans, mutations or partial deletion of titin might cause muscular dystrophies, such as Tibial Muscular Dystrophy (TMD) or limb-girdle muscular dystrophy 2J (LGMD-2J)." (PMID 31428229, 2019). "Tibial muscular dystrophy (TMD) is a late onset, autosomal dominant distal myopathy that results from mutations in the two last domains of titin." (PMID 24618559, 2014). "Furthermore, mutations in the MYH7 gene can potentially disrupt interactions between myosin and titin with myomesin, M-protein, or sarcomeric structures, leading to Laing Early-Onset Distal Myopathy (MPD1) and tibial muscular dystrophy." (PMID 39280835, 2024). "These myopathies are due to mutations in several genes, including dystrophin (Duchenne muscular dystrophy, DMD), calpain-3 (Limb girdle muscular dystrophies, LGMD2A), or titin [muscular dystrophy with myositis (MDM); tibial muscular dystrophy (TMD) and limb-girdle muscular dystrophy 2J (LGMD2J)]." (PMID 35846001, 2022).
familial dilated cardiomyopathy (20 papers, 2016 to 2025). A a genetic form of heart disease that occurs when heart (cardiac) muscle becomes thin and weakened in at least one chamber of the heart, causing the open area of the chamber to become enlarged (dilated). "Titin-truncating variants, yielding titin haploinsufficiency, are the most common causes of familial dilated cardiomyopathy." (PMID 40282425, 2025). "A comprehensive meta-analysis by Fang and Liu (2020) reveals a significant connection between TTN mutations and familial dilated cardiomyopathy (DCM)." (PMID 41190030, 2025). "Truncation variants in the gene TTN encoding titin are the most common cause of familial dilated cardiomyopathy (DCM), with both haploinsufficiency and “poison peptide” implicated as contributory mechanisms of disease." (PMID 39959973, 2025). "It is worth noting that TTN encodes for the giant sarcomeric protein titin and is regarded the cause of ≈25% of familial dilated cardiomyopathy." (PMID 36873395, 2023). "While TTN truncating variants (TTNtvs) are considered the most common cause of familial dilated cardiomyopathy (DCM), they can also account for up to 10% of ACM cases." (PMID 36835518, 2023). "Mutations within the TTN gene, that encodes the sarcomeric protein titin, are strongly linked to the development of familial dilated cardiomyopathy and atrial fibrillation." (PMID 35197863, 2022). "Most prevalent were TTN truncating variants (n = 5) which encode for the giant sarcomeric protein titin and are known to explain ca. 25% of patients with familial dilated cardiomyopathy." (PMID 35498019, 2022). "TTN truncating variants were responsible for about 25% of familial dilated cardiomyopathy and in 18% of sporadic cases." (PMID 36072675, 2022). "Advances in high throughput sequencing have made TTN more accessible for genetic analyses in clinical practice, revealing that up to 25% of familial dilated cardiomyopathy (DCM) cases are associated with truncating variants in TTN." (PMID 33637999, 2021). "RBM20 is highly expressed in the heart and mutations in RBM20 cause familial dilated cardiomyopathy (DCM) by promoting the expression of a long isoform of the sarcomere protein titin." (PMID 31717392, 2019). "In the general population, rare variants in TTN and BAG3 are associated with an increased risk of familial dilated cardiomyopathy, and common variants are associated with a decreased risk of sporadic dilated cardiomyopathy." (PMID 40540274, 2025). "In addition, the mutation of Titin could result in familial dilated cardiomyopathy." (PMID 31889968, 2019). "In a patient with familial dilated cardiomyopathy (DCM), a Gly48Ser mutation that impairs the interactions of FHL2 with the metabolic enzyme titin/connectin may lead to cardiac dysfunction and heart failure." (PMID 33932144, 2021). "OLA1 maps to chromosome 2 (locus 2q31.1), near Titin (TTN), which is associated with familial dilated cardiomyopathy (DCM) in humans." (PMID 38889130, 2024).
glioma (20 papers, 2019 to 2025). A benign or malignant brain and spinal cord tumor that arises from glial cells (astrocytes, oligodendrocytes, ependymal cells). "High expression of TTN has been reported in gliomas, while ABI2‐deficient mice exhibit difficulties in learning and memory." (PMID 37594177, 2023). "The frequency of mutations for PIK3CA, MUC16 and TTN was significantly higher in high risk glioma cases (TTN, 26% vs. 7%; MUC16, 16% vs. 8%; PIK3CA, 10% vs. 3%)." (PMID 33946049, 2021). "Another frequently mutated gene was TTN in all grades, which was also identified previously in glioma." (PMID 32047515, 2019). "In a computational study using TCGA (The Cancer Genome Atlas) glioma data, CRY1, BMAL1, and RORγ were associated with a higher mutation rate and mutation hotspots in EGFR, TTN (Titin), and PTEN (Phosphatase and Tensin Homologue) genes." (PMID 38378853, 2024). "The SHOX2high group (n = 175) showed high frequency of somatic mutations in the EGFR (40%), PTEN (36%), TTN (36%) and MUC16 (26%) genes in glioma." (PMID 37170390, 2023). "A high frequency of mutations in IDH1 and Chr1p19q was detected in gliomas with low PIEZO1 expression, while mutations in TTN, PTEN and NF1 were significantly enriched in cases with high expression of PIEZO1." (PMID 32999349, 2020). "The mutation frequencies of IDH1 and ATRX in gliomas with a low-risk score were remarkably higher than in gliomas with a high-risk score (IDH1, 92% vs. 31%; ATRX, 33% vs. 21%), while TTN and MUC16 had lower mutation frequencies (TTN, 8% vs. 21%; MUC16, 7% vs. 10%)." (PMID 36311792, 2022).
melanoma (20 papers, 2018 to 2025). A malignant, usually aggressive tumor composed of atypical, neoplastic melanocytes. "We performed mutation analysis on melanoma samples, identifying TTN, MUC16, and BRAF as the most frequently mutated genes among the top 30 somatic mutations." (PMID 40639089, 2025). "Among the melanoma patients, the most frequently mutated genes were TTN, MUC16, BRAF, DNAH5, and PCLO." (PMID 40781483, 2025). "Our study showed that MUC16 and TTN were the most common co‐occurrent mutations in this cohort of melanoma patients." (PMID 39240165, 2024). "TTN mutations are a potential marker of poor prognosis in melanoma, which is amplified in the presence of concurrent MUC16 mutations." (PMID 39240165, 2024). "We found that melanoma patients with TTN mutations alone and melanoma patients with both MUC16 and TTN mutations had worse prognosis than patients with neither MUC16 or TTN mutations." (PMID 39240165, 2024). "The most frequently mutated genes in human melanoma were those mutated in parental and dormant mouse cells (common genes), with up to 80% mutation rates for TTN, followed by PCLO (> 52%), DSCAM (approximately 40%), and OBSCN (approximately 34%)." (PMID 39223638, 2024). "The top 10 mutated genes in melanoma were TTN (72%), MUC16 (67%), DNAH5 (49%), PCLO (44%), LRP1B (38%), ANK3 (32%), DNAH7 (32%), ADGRV1 (35%), RP1 (33%), and BRAF (51%)." (PMID 33758620, 2021). "The top 10 mutated genes in 467 melanoma patients are TTN (72%), MUC16 (67%), BRAF (51%), DNAH5 (49%), PCLO (44%), LRP1B (38%), ADGRV1 (35%), RP1 (33%), ANK3 (32%), DNAH7 (32%)." (PMID 33072607, 2020). "While TTN mutation count has been proposed as a surrogate marker for tumor mutational burden (TMB) in hypermutated tumors such as melanoma and colorectal cancer, its correlation with TMB is markedly weaker in cancers with lower mutation rates, including breast, kidney, and thyroid cancers." (PMID 40312292, 2025). "Mutations in the MUC16 and TTN genes commonly occur concurrently in these melanoma patients, but their combined prognostic significance stratified by gender and cancer subtype remains unclear." (PMID 39240165, 2024). "Therefore, we investigated the impact the two most commonly co‐occurrent genetic mutations, MUC16 and TTN, on patient prognosis and the impact of gender and melanoma subtype on patient mortality risk." (PMID 39240165, 2024). "Interestingly, serum antibodies directed against TTN were found in patients with melanoma-associated retinopathy, suggesting TTN was a potential biomarker for melanoma and also an association with carcinogenesis." (PMID 35355511, 2022). "Therefore, our findings suggest that, although MUC16 and TTN mutations often occur concurrently, TTN mutations may be the primary driver of poor prognosis in melanoma patients." (PMID 39240165, 2024). "Mutation profiling revealed frequent alterations in TTN (72%), MUC16 (67%), BRAF (51%), and other melanoma-associated genes." (PMID 41150769, 2025). "TTN and MUC16 mutations were the most frequently mutated genes within this melanoma patient cohort and were the most common combination of concurrently mutated genes overall." (PMID 39240165, 2024). "Its high expression is correlated with poor overall survival (OS) of melanoma patients and promotes melanoma cell proliferation, migration and tumor progression in vivo by increasing the transcription of TTN." (PMID 35096622, 2021). "At the same time, the mutation rate of TTN and MUC16 will increase in patients with CDKN2A deletion, which suggests that the increased mutation of TTN and MUC16 in this study may lead to metastasis of melanoma." (PMID 36891324, 2023). "Mutation frequency analysis also revealed recurrent abnormalities in genes such as TTN, MUC16, and BRAF, which correspond to their recognized functions in melanoma development." (PMID 41150769, 2025).
melanoma (continued). "Subsequently, we conducted a joint analysis of proteomic data and TCGA human melanoma RNA-seq data, and found that the mRNA and protein levels of 34 genes, including DSE, VEPH1, SFRP4, TTN, STSE, were consistently down-regulated in melanoma tissues." (PMID 37833287, 2023). "Furthermore, the reported TMB-related genes including PAPPA2, KALRN, and TTN were significantly correlated with patient response in NSCLC, which were also identified in melanoma." (PMID 36139377, 2022).
myocarditis (19 papers, 2019 to 2026). Myocarditis is a condition that is characterized by inflammation of the heart muscle (myocardium). "Although these studies used DSP disruption as its genetic model of myocarditis, many other genes have been implicated in this process, including TTN, LMNA, FLNC, PKP2, and others." (PMID 38768074, 2024). "Moreover, nearly half of MG patients have antistriatal antibodies (e.g., against titin, ryanodine receptor, or voltage-gated potassium channel) that can bind to the heart muscle causing myocarditis." (PMID 34069830, 2021). "Finally, the incidence of myocarditis is higher with combination therapies and susceptibility may be influenced by variants in genes related to inflammation and cardiac structural integrity, such as titin (TTN)." (PMID 41598751, 2026). "Studies have reported that up to 22% of patients initially diagnosed with myocarditis carry such mutations, with DSP, LMNA, and TTN being the most frequently implicated genes." (PMID 41040932, 2025). "A critical example is a clinical trial targeting MAGE-A3, where 33% of patients developed fatal myocarditis due to cross-recognition of titin in cardiac muscle." (PMID 41262250, 2025). "Here, we explore this topic and give a data-based perspective, gathering a comparison between the titin protein of the sarcomere and myocarditis." (PMID 37601060, 2023). "All patients with MG tested positive for anti-AchR antibodies (mean titer: 1.84 nmol/L), while three patients with MG/myositis and concurrent myocarditis had anti-titin antibodies." (PMID 36800019, 2023). "Detected autoantibodies in patients with myositis, myocarditis or MG were anti-heart muscle (six cases), anti-skeletal muscle (six cases), anti-titin (five cases), anti-RyR (four cases), anti-AchR (three cases), and anti-LRP4 (one case) autoantibodies." (PMID 36845122, 2023). "In patients with immune checkpoint inhibitor (ICI)-related myocarditis and myositis, anti-titin and anti-potassium channel Kv1.4 antibodies are often detected." (PMID 37189393, 2023). "Cytometric cell-based assays revealed that 13 MG patients with myositis and/or myocarditis had both anti-titin and anti-Kv1.4 antibodies." (PMID 30918333, 2019). "Serial changes in the antibody index showed that anti-titin antibodies were present before the onset of myositis and myocarditis." (PMID 30918333, 2019). "Interestingly, we detected anti-titin antibodies in three out of four patients with MG/myositis/myocarditis (75%), confirming previous reports." (PMID 36800019, 2023). "In numerous cases of acute myocarditis, titin and the cytoskeleton are dysregulated." (PMID 37601060, 2023). "The mechanisms behind this failure may rely on the molecular mimicry as hypothesized for titin and myocarditis/pericarditis, but involving other antigenic determinants, which are chief to the formation of autoantibodies." (PMID 37601060, 2023). "Indeed, in a model of Coxsackie virus B3 (CVB3)-induced myocarditis, impaired titin phosphorylation was observed, along with LV dysfunction, increased cardiac inflammation, including IL-6 levels, and fibrosis." (PMID 37189393, 2023). "Anti-titin antibodies were detected in 93% (28/30) of MG patients with myositis and/or myocarditis." (PMID 30918333, 2019). "In addition, we emphasize that all MG patients with myositis and/or myocarditis had anti-titin or anti-Kv1.4 antibodies." (PMID 30918333, 2019).